FGF7 (fibroblast growth factor 7)
Diseases named in the same sentence as FGF7 in open-access papers (continued):
Sharing a sentence is not in itself a finding about the gene and the disease.
cancer (93 papers, 2007 to 2026). A tumor composed of atypical neoplastic, often pleomorphic cells that invade other tissues. "To determine the potential effects of fibroblast‐released FGF7 in EC, we investigated the influence of EC patient‐derived cancer‐associated fibroblasts (CAFs67) on the migration of invasive FGFR2‐mutant EC cells." (PMID 37165578, 2023). "Furthermore, consistent with our findings, previous studies have reported that OLR1 and FGF7 are associated with adverse cancer prognosis due to alterations in immune response and TME status." (PMID 38154113, 2023). "Similarly to soluble FGFs, cancer-associated fibroblast (CAFs), known to be a rich source of various FGFs (including FGF7), had an impact on PR expression." (PMID 27852068, 2016). "Inhibition of stromal PDGF receptors reduced proliferation and angiogenesis in cervical lesions through a mechanism involving suppression of expression of the angiogenic factor fibroblast growth factor 2 (FGF-2) and the epithelial cell growth factor FGF-7 by cancer-associated fibroblasts." (PMID 18232728, 2008). "Intriguingly, compared with the myoFib‐2 subgroup, myoFib‐1 displayed higher levels of FGF expression, with the most prevalently expressed FGF7, a crucial component in stimulating the proliferation of cancer cells." (PMID 38778448, 2024). "Overall, our study clearly configures a potential targeted signaling axis linking CAFs and ccRCC cancer cells, providing a rationale to develop FGF7-targeted therapy against ccRCC progression." (PMID 39594574, 2024). "Crucially, we introduce a novel mechanism wherein FGF7 serves as a critical regulatory factor facilitating crosstalk between CAFs and cancer cells, thereby promoting the progression of OC via activation of the HIF1α/EMT signaling axis." (PMID 38491511, 2024). "Despite its beneficial involvement in organogenesis and development, several cancers arise due to FGF7 overexpression." (PMID 39766329, 2024). "Although FGF7 expression is upregulated in many cancers, it is expressed at lower levels in EC by comparison with the corresponding normal tissue." (PMID 37165578, 2023). "Cancer-associated fibroblast (CAF) sub-clusters showing high expression of IL6, CCL2, S100A4, PDPN, and FGF7 were identified in both primary and metastatic samples." (PMID 38328306, 2023). "Conversely, EM cells as well as FGFR2‐WT EC cells formed only a few colonies even in the presence of FGF7, suggesting that other factors drive anchorage‐independent cell growth in these cancer cells." (PMID 37165578, 2023). "The second subset highly expressed FGF7 and was moderately protective of cancers, by moderately suppressing the immune system, while the last subset, presenting low level of FGF7 and HGF, scarcely suppressed the immune system." (PMID 35892828, 2022). "FGF7/10 can also induce cancer by affecting inflammatory cell properties via inflammatory responsiveness." (PMID 35492363, 2022). "The involvement of FGF7 and FGF9 secreted by cancer-associated fibroblasts were also demonstrated to promote migration and invasion of GC cells." (PMID 30082912, 2019). "Depletion of RB in CAFs enhances the invasive potential of cancer cells through increased production of CAF-derived keratinocyte growth factor (KGF or FGF7), that regulates invasion via an AKT–Ets2–matrix metalloproteinase (MMP)-1-dependent pathway." (PMID 25853091, 2015). "Either MUC1 or FGF7 knockdown impeded the migration‐promoting function of cancer cells and CAFs." (PMID 38778448, 2024). "However, abnormally high expression of FGF7, an important mitogen, promotes the invasion and migration of cancer cells, while inhibition of FGF7 signaling can reduce the migration of cancer cells." (PMID 38274662, 2023). "Subtype II expressed FGF7 and had moderate protection against cancer." (PMID 36185262, 2022).
cancer (continued). "Notably, FGF7 plays an important role in regulating the growth of the mammary epithelium and also contributes to mammary tumorigenesis, a cancer type in which PLAC1 is found to be frequently expressed." (PMID 32499871, 2020). "Meanwhile, FGF7 secreted from osteoclasts affected the receptor FGFR3 in cancer 4 cells." (PMID 33162821, 2020). "Instead, the Pathways in cancer genes Kras, Met, Figf, Hgf, Fgf7, Ctnnb1 and Tcf7l1, and directly interacting genes Nr3c2 and Csnk2a1 may lead to new insights in US28-mediated signaling and ultimately the oncomodulatory role of HCMV." (PMID 25002203, 2014). "Other experiments indicate that imatinib had these effects because its inhibition of stromal PDGF receptors suppressed the expression of FGF-7 (a factor that encourages epithelial cell division) and FGF-2 (a proangiogenic factor) by cancer-associated fibroblasts." (PMID 18232728, 2008). "Moreover, we knocked down MUC1 and FGF7 in MCA cancer cells and CAFs, respectively." (PMID 38778448, 2024). "To determine the clinical relevance of FGFR2 and FGF7 in RMS patient tumors, we analyzed gene expression data generated in the ITCC/CIT (Innovative Therapies for Children with Cancer/Carte d’Identite’ des Tumeurs) cohort." (PMID 34850536, 2022). "Increased gene levels of VEGF, FGF, FGF7, IGF1, and IGF2, known for their proliferation-promoting effects in endothelial, fibroblasts, and cancer cells, were also detected." (PMID 36010901, 2022). "Subtype I highly expressed hepatocyte growth factor (HGF) and fibroblast growth factor 7 (FGF7), and had strong protective effects against cancer." (PMID 36185262, 2022). "Next, we used cBioPortal to evaluate the correlations between the levels of FGL2 and the cancer-promoting cytokines measured above (IL-10, MMP9, CCL5, TIM-3, IL-13, VCAM1, M-CSF and FGF-7) in ESCA tissues." (PMID 33323552, 2020). "A comparison of genome-wide methylation profiles of NHK and cSCC cell lines revealed a statistically significant difference in methylation in 361 unique genes (adjusted p-value ≤ 0.01), including known cancer drivers (MAP2K2, WNT5A, COL4A1, BMP2 and FGF7)." (PMID 31336867, 2019). "Analysis of the cancer cell lines shows a variable, but widespread expression of MET and FGFR2, which are receptors for HGF and FGF7, respectively, across the panel of ESCC cell lines." (PMID 25884729, 2015). "Next, we examined the effects of adding growth factors HGF, FGF1, FGF7, and FGF10, to the culture medium of cancer cells." (PMID 25884729, 2015). "IFGBP4, TPO, BDNF, and FGF-7 demonstrated higher FF levels in adolescents without cancer compared to donors." (PMID 39211054, 2024). "BDNF and FGF-7 levels were also significantly higher in FF of adolescents without cancer compared to the adolescents with cancer." (PMID 39211054, 2024). "Notably, CD34, IL7R, NRP1, GZMB, FGF7, and ENO2 exhibited significant expression in cancer stem cells, CD4+ memory cells, regulatory T cells, NK cells, fibroblasts, and neurons, respectively." (PMID 38846945, 2024). "The exogenous addition of FGF7 and THBS1 protein enhanced the migration ability of cancer cells." (PMID 38778448, 2024). "In particular, FGF7 and FGF10 are reported to signal from the stroma to the cancer cells." (PMID 33918004, 2021). "In addition to metabolic reprogramming providing an energy source to foster cancer cells, TGF-β activated CAFs secrete growth factors, such as TGF-β, FGF2, FGF7, VEGF, PDGF, and HGF, to promote cancer cell proliferation." (PMID 33322749, 2020). "So far no patients conditioned with short acting FGF7 have acquired new or different types of cancer afterwards." (PMID 28207794, 2017). "Importantly, target genes involved in epithelium development (RGMA, SHANK3, PAX6, PFN1, WNT4) and cancer (CBL, CYCS, FGF7, IGF1R, PTEN, PIK3CD, WNT4) address to a further role in the onset of epithelial abnormalities and oncogenesis." (PMID 23936163, 2013).
cancer (continued). "Genes such as RLIM, FBL17, FGF7, DDX5, NAV3, and NFASC were found at the intersection of multiple pathways, suggesting they may function as critical effectors of miR-155 and miR-3173 activity in cancer." (PMID 40722677, 2025). "The OD-BRE-0438 model with the most resistant phenotype, as evidenced by the shortest median PFS, showed statistically significant upregulated gene expression of FGF1, FGF7, and FGF8 ligands in cancer cells, while FGFR1, FGFR2, or FGFR3 were not upregulated." (PMID 40227585, 2025). "While no anti-FGF7 drugs are currently in clinical trial, several anti-FGFR therapies have proven effective in phases I–III trials for various cancer types leading to multiple FDA approvals." (PMID 39886662, 2024). "The culture supernatants of measured cancer cells (KYSE30, KYSE50, KYSE150, KYSE220, T.TN, TE-8, TE-11, TE-14, and TE-15) contained virtually no HGF or FGF7, suggesting that the autocrine activity of these cells was minimal." (PMID 25884729, 2015). "However, since normal ovarian surface epithelium does not express the IIIb isoform of FGFR2, it cannot respond to FGF7, and therefore, FGFR2-IIIb represents a rational cancer drug target." (PMID 39886662, 2024).
infection (19 papers, 2012 to 2025). The state of being infected such as from the introduction of a foreign agent such as serum, vaccine, antigenic substance or organism. "Based on these findings, we developed a sustained-release formulation using GelMA to avoid the need for repetitive injections, thereby mitigating pain and infection, and enhancing the longevity of FGF7’s bioactivity." (PMID 41455730, 2025). "IF staining also demonstrated that the viral N-protein infection ratio in FGF7-treated islets was ~3 times greater than that in G1 and G5 islets." (PMID 38654010, 2024). "FGF7 suppressed ISG expression and caused a robust increase in HSV‐1 DNA when added together with the virus or 2–4 h post‐infection and was thus present for 8–12 h." (PMID 32720440, 2020). "qRT–PCR analysis of ZIKV RNA demonstrated that FGF7 was also effective when added 2 h after infection." (PMID 32720440, 2020). "Similarly, the activation of genes such as Serping1, Sparc, Pcsk5, Fgf7, and Cyp7b1 indicated the temporal activation of cell migration and immune suppression during infection." (PMID 38767331, 2024). "Indeed, we previously showed that FGFR kinase inhibitors suppress the infection of keratinocytes with herpes simplex virus I, while FGF7 or FGF10 had the opposite effect." (PMID 39340759, 2024). "However, when FGF7 was added 8 h post‐infection, suppression of ISG expression and promotion of viral replication was no longer observed." (PMID 32720440, 2020). "The engineered cell line producing engineered exosome was developed by infection with lentivirus containing three cargo genes (WNT10B, FGF7, and VEGFA) in HEK-293 cells." (PMID 40521098, 2025). "Two of these genes, Fibroblast growth factor 9 (fgf9) and Keratinocyte Growth Factor (fgf7) were upregulated in the ear >40-fold 5d post-VACV infection in WT mice." (PMID 38543790, 2024). "Prior to infection with live SARS-CoV-2, the islet organoids were pretreated with FGF7 and/or FGFR inhibitors for 3 days to either activate or suppress the FGF7-FGFR pathway." (PMID 38654010, 2024). "ADAM17 activity can be triggered by factors such as apoptosis, Ang II, D-glucose, IL-1β, Ca2+ ionophores, fibroblast growth factor 7 (FGF7), protein kinase C (PKC) activators, and purine receptor 2 (P2) agonists during pathogen infection through toll-like receptors (TLRs)." (PMID 41303587, 2025). "In EAE mice, infection increased the level of FGF-2 and FGF-7 in CSF." (PMID 36836678, 2023). "In contrast to the upregulation of ACE2 induced by FGF7 in the absence of SARS-CoV-2, both the gene and protein levels of ACE2 in G4 islet organoids were significantly reduced after infection." (PMID 38654010, 2024).
adenocarcinoma (4 papers, 2009 to 2020). A common cancer characterized by the presence of malignant glandular cells. "The fourth network in adenocarcinomas depicts several ligands of tyrosine kinases like Fgf7 (fibroblast growth factor 7) and Pdgfbb (platelet derived growth factor, B polypeptide) as regulated." (PMID 19812696, 2009). "Indeed, constitutive overexpression of FGF7 in the mammary epithelium of transgenic mice induces mammary hyperplasia and adenocarcinoma." (PMID 32499871, 2020). "Besides the significantly up-regulation of Areg and Ereg, we found fibroblast growth factor 7 −5.4-fold-down-regulated in adenocarcinoma and −6.4-fold down-regulated in adenocarcinoma vs non-transgenic cells." (PMID 19812696, 2009).
bacterial infections (3 papers, 2021 to 2024). "In addition, migrating Vγ9Vδ2 T cells can locally produce fibroblast growth factor-7 (FGF-7), a homeostatic mediator against tissue damages induced by bacterial infections." (PMID 35924233, 2022).
hematologic malignancies (3 papers, 2013 to 2022). "FGF7 has FDA approval and held a license for severe oral mucositis in patients with hematologic malignancies receiving myelotoxic therapy." (PMID 33428803, 2021).
urinary tract diseases (1 paper, 2023). "Further studies on the Fgf7-PPARγ signaling axis would provide insights into the differentiation mechanisms toward functional umbrella cells and the pathogenesis of several urinary tract diseases." (PMID 37875848, 2023).
FGF7 also shares sentences with these, for which no sentence is quoted: psoriasis (11 papers); acute respiratory distress syndrome (7); acute lung injury (6); cholesteatoma (6); pneumonia (6); fibrosis (5); inflammation (5); melanoma (5); inflammatory bowel disease (4); Sepsis (4); graft versus host disease (3); hematologic cancers (3); hypophosphatemia (3); influenza (3); lymphoma (3); Obesity (3); squamous cell carcinoma (3); ulcerative colitis (3); acute GVHD (2); bacterial pneumonia (2); gastric adenocarcinoma (2); gingival enlargement (2); head and neck cancer (2); Hyperglycemia (2); hyperphosphatemia (2); lung disorder (2); melasma (2); myxoid liposarcoma (2); periapical granuloma (2); X-linked hypophosphatemic rickets (2).
A further 84 diseases each share a sentence with FGF7 in 1 paper.